DMD (dystrophin)
Diseases named in the same sentence as DMD in open-access papers (continued):
Sharing a sentence is not in itself a finding about the gene and the disease.
Duchenne muscular dystrophy (continued). "This agrees with the pathobiochemical concept that the almost complete absence of dystrophin is the main defect in Duchenne muscular dystrophy and that the mdx-4cv mouse model of dystrophinopathy exhibits only very few revertant fibers." (PMID 28248273, 2015). "Duchenne Muscular Dystrophy (DMD) is a fatal neuromuscular disease characterised by progressive fibre necrosis secondary to the absence of the protein dystrophin from the sarcolemma." (PMID 25541951, 2014). "Duchenne muscular dystrophy (DMD) is a genetic disorder characterized by absence of the cytoskeletal protein dystrophin." (PMID 24695436, 2014). "Lack of dystrophin results in a progressive skeletal muscle wasting disease called Duchenne muscular dystrophy (DMD)." (PMID 25054970, 2014). "Duchenne muscular dystrophy (DMD) is a neuromuscular disease that arises due to the absence of the protein dystrophin." (PMID 25260053, 2014). "Duchenne muscular dystrophy is a well-known inherited muscle disease that results from the lack of functional dystrophin proteins." (PMID 24273513, 2013). "A lack of dystrophin has been shown in patients with Duchenne muscular dystrophy and in animal models of this disease which consequently leads to a loss of nNOS from the sarcolemma." (PMID 23538841, 2013). "Duchenne muscular dystrophy (DMD) is a lethal muscle degenerative disease that arises from mutations, typically large deletions, in the DMD gene resulting in out-of-frame dystrophin transcripts and ultimately in the lack of functional dystrophin protein." (PMID 23658612, 2013). "Perhaps the most well-known case is in Duchenne muscular dystrophy, where the dystrophin (DMD) protein is not expressed leading to aberrant Golgi organization." (PMID 24025425, 2013). "The lack of dystrophin in the hearts of patients with Duchenne muscular dystrophy (DMD) as well as in mdx mice constitutes the structural basis for the development of dilated cardiomyopathy." (PMID 23935889, 2013). "Duchenne muscular dystrophy (DMD) is the most common X-linked muscle degenerative disease and it is due to the absence of the cytoskeletal protein dystrophin." (PMID 23363418, 2013). "Absence of dystrophin makes skeletal muscle more susceptible to injury, resulting in breaches of the plasma membrane and chronic inflammation in Duchenne muscular dystrophy (DMD)." (PMID 24014378, 2013). "Duchenne muscular dystrophy (DMD), one of the most common and lethal genetic disorders, and the mdx mouse myopathies are caused by a lack of dystrophin protein." (PMID 23894429, 2013). "Duchenne muscular dystrophy (DMD) is the most common muscular dystrophy and an X-linked recessive, progressive muscle wasting disease caused by the absence of a functional dystrophin protein." (PMID 23618411, 2013). "Primary abnormalities in the dystrophin gene lead to a functional absence of the full-length Dp427 isoform and trigger Duchenne muscular dystrophy, a progressive neuromuscular disease of childhood." (PMID 22614334, 2012). "Overexpression of Bcl-2 had no major effect in dystrophin-deficient mice, indicating that Bcl-2-mediated apoptosis is a more significant contributor to the pathogenesis of MDC1A than that of Duchenne muscular dystrophy." (PMID 21798088, 2011). "It was not until the discovery of dystrophin as the relevant protein missing in Duchenne muscular dystrophy (DMD) and the isolation of the dystrophin glycoprotein complex (DGC) that this group was further stratified according to the molecular defect." (PMID 21798091, 2011). "In mdx mice and humans afflicted by Duchenne muscular dystrophy the absence of dystrophin leads to sarcolemmal damage and increased membrane permeability, thereby elevating serum CK." (PMID 20161803, 2010).
Duchenne muscular dystrophy (continued). "Patients with Duchenne muscular dystrophy (DMD) may experience neurobehavioral and cognitive concerns, including psychiatric symptoms, due to the absence of full‐length dystrophin (Dp427), frequently accompanied by deficiencies in shorter isoforms." (PMID 40913379, 2025). "Duchenne muscular dystrophy (DMD) is an X-linked genetic disorder caused by mutations in the DMD gene, which results in the absence of the structural protein dystrophin and the dismantling of the dystrophin-associated oligomeric protein complex at the sarcolemma." (PMID 41300182, 2025). "In neuromuscular disorders such as Duchenne muscular dystrophy (DMD) and myotonic dystrophy type 1 (DM1), AOCs promote exon skipping or RNA interference, restoring dystrophin expression or reducing toxic RNA repeats in vivo." (PMID 41219972, 2025). "Duchenne muscular dystrophy (DMD) is frequently associated with neurobehavioral and cognitive impairments, including psychiatric symptoms, resulting from the absence of full‐length dystrophin, alone or in combination with its shorter isoforms." (PMID 40913379, 2025). "Duchenne muscular dystrophy (DMD) is a neuromuscular condition caused by mutations in the DMD gene, resulting in a lack of dystrophin, a key component of the dystrophin-associated protein complex (DAPC) localized in the cortical cytoskeleton of skeletal myofibers and cardiomyocytes." (PMID 38247849, 2024). "We have previously reported the proof-of-concept studies testing a new chimeric cell line of the dystrophin expressing chimeric (DEC) cells, created by fusion of human myoblasts derived from duchenne muscular dystrophy (DMD) patients and normal healthy donors." (PMID 38791026, 2024). "CNVs were detected affecting genes where deletions or duplications are established as a common mechanism, like PRKN (in Parkinson’s disease), DMD (in Duchenne muscular dystrophy) and PMP22 (in neuropathies), but also genes in which no intragenic CNVs have been reported to date." (PMID 36781956, 2023). "Duchenne muscular dystrophy is caused by mutations in the DMD gene, leading to lack of dystrophin." (PMID 37582915, 2023). "In Duchenne muscular dystrophy (DMD), approved ASO therapies utilize a stabilized oligonucleotide chemistry known as phosphorodiamidate morpholino oligomers (PMOs) to enable frameshift correction by exon skipping, ultimately resulting in production of a truncated but functional dystrophin protein." (PMID 37538053, 2023). "The most prevalent pediatric muscle wasting disease, Duchenne muscular dystrophy (DMD), is a lethal X-linked disorder that affects all muscles due to mutations in the gene encoding dystrophin and is an example of a disorder that does not affect all muscles equally." (PMID 37641124, 2023). "Increased ST2 levels were found in sera of patients affected by Duchenne muscular dystrophy (DMD), a rare and fatal X-linked disorder characterized by the lack of dystrophin, a key sarcolemma muscle protein, in which cardiac failure represents a significant cause of death." (PMID 37371771, 2023). "CD4+ and CD8+ T cells have also been associated with muscle degeneration and fibrosis in the mdx mice, a natural mutant that does not express dystrophin and Duchenne muscular dystrophy (DMD) homolog, by induction of specific antigen activation of CD44+ cells homing into the damaged tissue." (PMID 35740942, 2022). "Consequently, the lack of dystrophin increases the chance of sarcolemmal rupture following skeletal muscle contraction, a characteristic feature of Duchenne muscular dystrophy." (PMID 35419431, 2022). "Background: the present study aims to assess language in preschool-aged Duchenne muscular dystrophy (DMD) boys with normal cognitive quotients, and to establish whether language difficulties are related to attentional aspects or to the involvement of brain dystrophin isoforms." (PMID 36138988, 2022).
Duchenne muscular dystrophy (continued). "On the other hand, the most common and severe form of genetic dystrophy in childhood is Duchenne muscular dystrophy (DMD, ONIM: #310200), affecting around 1 in 5000 new‐born boys and caused by mutations in the dystrophin gene that result in the complete absence of the protein." (PMID 35092179, 2022). "Duchenne muscular dystrophy (DMD), the most common form of muscular dystrophy, is caused by the absence of the protein dystrophin, which plays a mechanical role in linking the contractile apparatus inside the muscle fiber to the extracellular matrix outside the muscle fiber." (PMID 34360831, 2021). "In a mouse model of Duchenne muscular dystrophy (DMD), a single dose of 5 μg of Pip2a–PNA and Pip2b–PNA conjugates showed a significant increase in the dystrophin-positive myofibers." (PMID 34367346, 2021). "For instance, Duchenne Muscular Dystrophy (DMD) is a genetic myopathy where the complete absence of the protein dystrophin induces recurrent degeneration and regeneration cycles that are associated with tissue architecture remodeling, loss of function and progressive weakness." (PMID 33456578, 2021). "Similarly, in Duchenne muscular dystrophy, a variety of CRISPR-based methods have successfully restored dystrophin expression in iPSC models which was subsequently confirmed in murine and larger mammal models with current research focusing on clinical translation." (PMID 34713254, 2021). "Duchenne muscular dystrophy (DMD) is an X-linked, severe neuromuscular disorder with an incidence of 1:5000 newborn males due to genetic defects in the DMD gene, resulting in lack of functional dystrophin protein." (PMID 33362201, 2020). "The severity of Duchenne muscular dystrophy (DMD), an incurable disease caused by the lack of dystrophin, might be modulated by different factors, including miRNAs." (PMID 32493839, 2020). "Duchenne muscular dystrophy (DMD) is an X-linked muscle disorder that presents clinically with significant and progressive muscle wasting and loss of muscular function, due to the absence of the protein, dystrophin." (PMID 32760246, 2020). "Duchenne muscular dystrophy (DMD) is a progressive x-linked muscle-wasting disease that affects approximately one in 4000 male births in which mutations in the dystrophin gene result in production of a truncated, non-functional dystrophin protein." (PMID 32718931, 2020). "Herein, Duchenne muscular dystrophy has been taken as a paradigm, as several drugs have been tested at the preclinical and clinical levels, targeting secondary events in the complex pathogenesis derived from lack of dystrophin." (PMID 32660168, 2020). "Dystrophin expression was reduced (approximately 30 fold decrease in males and 2.5 fold decrease in females) and the observed phenotype seems to mimic the absence of dystrophin in Duchenne Muscular Dystrophy." (PMID 30820362, 2019). "Recently, Exondys51, a drug that aims to correct splicing defects in the dystrophin gene was approved by the US Food and Drug Administration (FDA) for the treatment of Duchenne muscular dystrophy (DMD)." (PMID 30988454, 2019). "In Duchenne muscular dystrophy, where dystrophin is lacking, utrophin is strikingly upregulated." (PMID 30764835, 2019). "Another example is the Duchenne muscular dystrophy (DMD) monkey model, successful created by CRISPR/Cas9-mediated deletion of the dystrophin gene." (PMID 34691891, 2019). "To determine which aspects of oligodendrocyte development and myelination might require the presence of dystrophin, an intracellular binding partner for dystroglycan, we evaluated postnatal brain development in mdx mice, a mouse model of Duchenne muscular dystrophy (DMD)." (PMID 28806929, 2017). "Exon skipping is a promising therapeutic strategy for Duchenne muscular dystrophy (DMD), employing morpholino antisense oligonucleotides (PMO-AO) to exclude disruptive exons from the mutant DMD transcript and elicit production of truncated dystrophin protein." (PMID 29038471, 2017).
Duchenne muscular dystrophy (continued). "Duchenne muscular dystrophy (DMD), caused by a lack of the functional structural protein dystrophin, leads to severe muscle degeneration where the patients are typically wheelchair-bound and die in their mid-twenties from cardiac or respiratory failure or both." (PMID 26316011, 2015). "Duchenne muscular dystrophy (DMD), the most common and severe type of dystrophinopathy, is an X-linked recessive genetic disease caused by the absence of dystrophin, which leads to fragility and vulnerability of the sarcolemma to mechanical stretching with increased membrane permeability." (PMID 25775477, 2015). "The absence of dystrophin results in Duchenne muscular dystrophy (DMD)." (PMID 24516626, 2014). "Duchenne Muscular Dystrophy is a chronic, progressive and ultimately fatal skeletal muscle wasting disease characterised by sarcolemmal fragility and intracellular Ca2+ dysregulation secondary to the absence of dystrophin." (PMID 25541951, 2014). "Duchenne muscular dystrophy (DMD) is a severe and progressive muscle-wasting disorder caused by mutations in the dystrophin gene that result in the absence of the membrane-stabilising protein dystrophin." (PMID 24476069, 2014). "Duchenne Muscular Dystrophy (DMD) is a common, inherited, incurable, fatal muscle wasting disease caused by deletions that disrupt the reading frame of the DMD gene such that no functional dystrophin protein is produced." (PMID 22274137, 2012). "In Duchenne muscular dystrophy patient, muscle cells are lacking dystrophin." (PMID 23209572, 2012). "Duchenne muscular dystrophy (DMD) is characterized by the absence of dystrophin in muscles." (PMID 22052037, 2011). "For example, Duchenne muscular dystrophy pathogenesis may involve proteasomal degradation of dystrophin and the DGC, and autophagy is impaired (but not increased as in MDC1A) in collagen VI-deficient muscular dystrophy." (PMID 21798088, 2011). "Duchenne muscular dystrophy (DMD), a degenerative muscle disorder caused mainly by nonsense or frame-shift mutations of the dystrophin gene, is one of the diseases that could be treated by AON-mediated exon skipping." (PMID 20805873, 2010). "Duchenne muscular dystrophy (DMD) is caused by the absence of the cytoskeletal protein, dystrophin." (PMID 19849858, 2009). "The mdx mouse, a commonly used genetic model for Duchenne muscular dystrophy (DMD), lacks dystrophin by virtue of a premature termination codon (PTC) in exon 23 that also severely reduces the level of dystrophin mRNA." (PMID 17487273, 2007). "To verify dystrophin deficiency in Duchenne muscular dystrophy (DMD) tissue, we conducted an immunohistochemical (IHC) staining assay against dystrophin on muscle sections derived from intercostalis (INT) and pectoralis (PECT) muscle samples of male DMD (n = 6) and wild-type (WT; n = 6) animals." (PMID 40558519, 2025). "In the context of Duchenne muscular dystrophy (DMD)—related cardiomyopathy—patient-derived iPSC-CMs have been utilized to evaluate exon-skipping oligonucleotides and CRISPR-mediated gene editing approaches aimed at restoring dystrophin expression." (PMID 40507801, 2025). "Duchenne muscular dystrophy (DMD) is caused by mutations in the DMD gene (HGNC:2928), leading to the absence of functional dystrophin and impairing both skeletal and cardiac muscle function." (PMID 39857686, 2025). "In genetic conditions like Duchenne Muscular Dystrophy (DMD), progressive muscle weakness and wasting occur, specifically affecting the structural integrity of fast‐twitch muscle fibres due to a lack of the dystrophin protein." (PMID 41229364, 2025). "Duchenne muscular dystrophy (DMD) is a genetic disorder characterized by the absence of the dystrophin protein, which is crucial for muscle stability." (PMID 41211267, 2025).
Duchenne muscular dystrophy (continued). "Background/Objectives: The progressive life-limiting disorder Duchenne muscular dystrophy (DMD) arises from the absence of dystrophin protein at the muscle cell membrane, which leads to progressive contraction-induced damage." (PMID 41300182, 2025). "Duchenne muscular dystrophy (DMD) is a severe genetic disorder characterized by the progressive degeneration of skeletal and cardiac muscles due to the absence of dystrophin." (PMID 40141224, 2025). "For Duchenne muscular dystrophy, a single dose of AAV9-micro dystrophin (5E + 13vg/kg) was tested in non-ambulatory adolescent DMD patients and transient renal dysfunction and hematological complications appeared few days post-administration." (PMID 38702726, 2024). "DYS is reported to be closely related to the human disease Duchenne muscular dystrophy (DMD); muscle cells of DMD patients are abnormally fragile because of the lack of dystrophin." (PMID 38720339, 2024). "Similarly, Duchenne muscular dystrophy (DMD) has seen significant progress, most notably with the FDA approval of delandistrogene moxeparvovec, the first micro-dystrophin gene therapy." (PMID 39593150, 2024). "Absence of dystrophin results in muscular weakness, chronic inflammation and cardiomyopathy in Duchenne muscular dystrophy (DMD)." (PMID 38770680, 2024). "Indeed, preventing this phosphorylation event or proteasomal degradation both appear to maintain βDG and the DGC at the sarcolemma, where it can maintain membrane integrity in the absence of dystrophin, as in animal models of Duchenne muscular dystrophy (DMD;)." (PMID 38474395, 2024). "An example is Duchenne Muscular Dystrophy (DMD) in which lack of dystrophin results in devastating skeletal muscle wasting in some muscles whereas others are spared or undergo hypertrophy." (PMID 37641124, 2023). "Duchenne Muscular Dystrophy (DMD) is a genetic disease characterized by progressive muscle degeneration and weakness due to the absence of dystrophin protein." (PMID 37228827, 2023). "As a case in point, in a mouse model of Duchenne muscular dystrophy (DMD), the absence of dystrophin in cardiomyocytes resulted in the emergence of a senescent phenotype." (PMID 37887886, 2023). "There are multiple types of muscular dystrophies, the most common one being Duchenne muscular dystrophy (DMD), which is also one of the most severe forms and is characterized by the complete or partial lack of dystrophin protein." (PMID 37371191, 2023). "The lack of dystrophin in Duchenne muscular dystrophy (DMD) results in membrane fragility resulting in contraction-induced muscle damage and subsequent inflammation." (PMID 35327337, 2022). "In Duchenne muscular dystrophy (DMD), a lack of functional dystrophin leads to myofiber instability and progressive muscle damage that results in fibrosis." (PMID 36302059, 2022). "Duchenne muscular dystrophy (DMD) is a degenerative genetic myopathy characterized by complete absence of dystrophin." (PMID 36142754, 2022). "Duchenne muscular dystrophy (DMD) is characterized by the absence of dystrophin, a cytoskeletal protein that organizes dystrophin-glycoprotein complexes (DGCs) in several tissues, with a prominent role in skeletal and cardiac muscle." (PMID 36430996, 2022). "GRMD dogs are characterized by a complete absence of dystrophin and provide a severe preclinical model of Duchenne muscular dystrophy (DMD)." (PMID 35459219, 2022). "Duchenne muscular dystrophy (DMD) affects approximately 1 in 3500 males and is characterized by progressive muscle weakness and wasting due to the lack of dystrophin protein." (PMID 34575143, 2021). "Duchenne muscular dystrophy (DMD) is a progressive wasting muscle disease characterized by fragile plasma membranes due to a lack of the structural protein dystrophin in myofibers." (PMID 35095541, 2021).